ENSG00000281516
Synonyms: LOC124900527
Gene: Small Cajal body-specific RNA gene on chromosome 2 (130,929,762 to 130,929,884, reverse strand). Ensembl gene ENSG00000281516.
Gene Ontology:
Biological process: RNA processing
Cellular component: Cajal body; nucleolus
Homologues: Orthologues: mouse Gm25820 (83% identical). Paralogues in human: SCARNA4 (89% identical).